OTOP1 (otopetrin 1)
Description:
Proton-selective ion channel. Biphasically modulated by acid and alkali, mediating proton influx and efflux in response to extracellular acid and base stimulation, respectively. Sour taste receptor, which carries inward currents in response to extracellular acidification (By similarity). Sensor for ammonium chloride (NH(4)Cl) in taste receptor cells. NH(4)Cl acts by increasing the intracellular pH, thereby generating a driving force for proton entry through OTOP1 channel. Might also participate in alkaline sensation. Plays a role in the regulation of Ca(2+) flux in response to purigenic (ATP, ADP and UDP) stimuli, leading to increase in cytosolic Ca(2+) due to influx of extracellular calcium. May play this role by inhibiting P2Y purinoceptor-mediated Ca(2+) release in a Ca(2+)- dependent manner and promote an influx of Ca(2+) in response to ATP. Through this mechanism and possibly others, plays a role in the formation and function of calcium carbonate-based structures in the vestibular system of the inner ear, called otoconia, that sense gravity and linear acceleration. In obesity, may attenuate adipose tissue inflammation, through the negative regulation of IFNG signaling, hence may play an adaptive role in the maintainance of metabolic homeostasis. Following alkali activation, may also be permeable Na(+), K(+), Cs(+) and Li(+) (By similarity).
Tractability: Antibody: UniProt places it where antibodies can reach, with high confidence; its Gene Ontology location is reachable by antibodies, with high confidence; UniProt predicts a signal peptide or a membrane-spanning region.
Gene: Protein-coding gene on chromosome 4 (4,188,726 to 4,226,929, reverse strand). Ensembl gene ENSG00000163982.
Subcellular location: Cell membrane; Cell projection, microvillus
Pathways (Reactome):
Sensory Perception: Sensory perception of sour taste
Gene Ontology:
Molecular function: proton channel activity; identical protein binding
Biological process: proton transmembrane transport; cellular response to insulin stimulus; negative regulation of type II interferon-mediated signaling pathway; otolith formation; otolith mineralization; otolith development; swimming behavior
Cellular component: plasma membrane; membrane; microvillus
Genetic constraint (gnomAD): Loss-of-function variants: 58 observed, 44.24 expected, observed/expected ratio (o/e) 1.31, 90% interval 1.06 to 1.63. The upper end of that interval is the gene's LOEUF score, 1.63, which puts it in group 6 of 6, group 1 being the genes least tolerant of losing a copy. Missense variants: 758 observed, 730.26 expected, observed/expected ratio (o/e) 1.04, 90% interval 0.98 to 1.1. Synonymous variants: 317 observed, 287.41 expected, observed/expected ratio (o/e) 1.1, 90% interval 1 to 1.21.
Homologues: Orthologues: chimpanzee OTOP1 (99% identical), macaque OTOP1 (94% identical), dog OTOP1 (83% identical), pig OTOP1 (82% identical), mouse Otop1 (77% identical), rat Otop1 (77% identical), rabbit OTOP1 (74% identical), guinea pig OTOP1 (70% identical), tropical clawed frog otop1 (61% identical), zebrafish OTOP1 (31% identical), Caenorhabditis elegans otpl-3 (16% identical), Caenorhabditis elegans otpl-2 (16% identical), and 4 more. Paralogues in human: OTOP2 (31% identical), OTOP3 (29% identical).
Diseases named in the same sentence as OTOP1 in open-access papers:
OTOP1 is named in the same sentence as 15 diseases in open-access papers, as found by Europe PMC text mining. Sharing a sentence is not in itself a finding about the gene and the disease. The quoted sentences say what the papers report.
Vertigo (3 papers, 2021 to 2023). An abnormal sensation of spinning while the body is actually stationary. "In our cohort 1, patient 5, who has a rare OTOP1 missense variant, reported vertigo symptoms during gymnastic maneuvers, suggesting possible otolith dysfunction in the semicircular canals." (PMID 37107589, 2023). "Recently a common variant rs2272744 upstream of OTOP1 was associated with vertigo in adult individuals of European descent in a genome-wide meta-analysis." (PMID 37107589, 2023). "Additionally, a male Spanish patient with the onset of symptoms of Meniere’s disease at 42 years old and a maternal family history of vertigo and deafness also had a rare OTOP1 missense variant." (PMID 37107589, 2023). "Variants in OTOG and otogelin like (OTOGL), otopetrin 1 (OTOP1), tectorin α (TECTA), zinc finger protein 91 (ZNF91), and armadillo repeat containing 9 (ARMC9) were associated with vertigo in a recent genome-wide meta-analysis." (PMID 35741759, 2022). "The vertigo association with the sequence variants at ZNF91, OTOP1, and OTOGL appears to be driven by their risk of BPPV." (PMID 34620984, 2021).
deafness (2 papers, 2011 to 2023). An inherited or acquired condition characterized by the complete loss of the ability to hear from one or both ears. "We also extended our evolutionary studies to the Ush1g deafness gene because of the tight head-to-tail physical clustering of Ush1g with Otop2 and Otop3 in vertebrate genomes, and because mutations in Otop1 and Ush1g result in inner ear phenotypes in vertebrates." (PMID 21261979, 2011).
cervical carcinoma (1 paper, 2021). A carcinoma arising from either the exocervical squamous epithelium or the endocervical glandular epithelium. "The increased sample size enabled identification of SMGs previously unreported in cervical carcinoma including NBPF10 (8%), RANBP2 (6%), MSN (6%), KRT8 (6%), POTEC (6%), ZC3H11A (4%), BMS1 (4%), GPX1 (3%), OTOP1 (3%), DNAH12 (2%), COIL (2%), TBC1D26 (2%), SPRED3 (2%), FAM115A (2%), and ARIH1 (1%)." (PMID 34620846, 2021).
dental caries (1 paper, 2022). The decay of a tooth, in which it becomes softened, discolored, and/or porous. "Results from this study suggest that the link between salt and sour taste variability and dental caries risk/protection may be related to the role of OTOP1 and SCNN1s variants in influencing the composition of the oral microbiome and this should be further explored in future studies." (PMID 36404915, 2022).
Hearing impairment (1 paper, 2011). A decreased magnitude of the sensory perception of sound. "Mutations in the Otopetrin 1 gene (Otop1) in mice and fish produce an unusual bilateral vestibular pathology that involves the absence of otoconia without hearing impairment." (PMID 21261979, 2011).
Insulin resistance (1 paper, 2023). Increased resistance towards insulin, that is, diminished effectiveness of insulin in reducing blood glucose levels. "No increase in insulin resistance was observed in the Otop1-/- mice." (PMID 37812612, 2023).
Meniere disease (1 paper, 2023). A disease of the inner ear (labyrinth) that is characterized by fluctuating sensorineural hearing loss; tinnitus; episodic vertigo; and aural fullness. "Additionally, a rare variant, OTOP1 c.380A>T (p.(His127Leu)), was found in a sporadic patient suffering from bilateral Meniere’s disease since the age of 42." (PMID 37107589, 2023). "Rare variants within ECM1, OTOP1, and OTOP2 were each identified in three adult patients with Meniere’s disease." (PMID 37107589, 2023). "Three genes, ECM1, OTOP1, and OTOP2, harbored rare variants in Spanish patients with Meniere’s disease." (PMID 37107589, 2023).
migraine (1 paper, 2023). "It should be noted that patient 5 had variants in one migraine gene, SLC35D2, and two inner ear genes, OTOP1 and LAMA2." (PMID 37107589, 2023).
Obesity (1 paper, 2023). Accumulation of substantial excess body fat. "Otop1 (Otopetrin 1) as a unique target of cytokine signaling can reduce the adipose tissue inflammation caused by obesity." (PMID 36991462, 2023).
polycystic kidney disease 2 (1 paper, 2021). Autosomal dominant polycystic kidney disease caused by a mutation in PKD2. "The polycystic kidney disease 1 and polycystic kidney disease 2–like proteins PKD2L1 and PKD1L3 have been identified as sour taste‐related receptors in human taste cells, and potential ion‐channel OTOP1 was present in taste cells in mouse that express Pkd2l1." (PMID 34401081, 2021).
scoliosis (1 paper, 2023). A congenital or acquired spinal deformity characterized by lateral curvature of the spine. "Additionally, an OTOP1 variant was identified in 11 adolescents with lateral semicircular canal asymmetry, 10 of whom have scoliosis." (PMID 37107589, 2023).
OTOP1 also shares sentences with these, for which no sentence is quoted: glioma (1 paper); kidney disease (1); polycystic kidney disease (1); Wolf-Hirschhorn syndrome (1).